CFTR (CF transmembrane conductance regulator)
Diseases named in the same sentence as CFTR in open-access papers (continued):
Sharing a sentence is not in itself a finding about the gene and the disease.
hematopoietic diseases (1 paper, 2018). "Therefore, CFTR may be a potential target for diagnosis and treatment of related hematopoietic diseases." (PMID 29449653, 2018).
mitochondrial disease (1 paper, 2022). "Before the cloning of CFTR, which allowed to demonstrate its role as a PManion channel, CF was thought to be a mitochondrial disease given the observed impairment of cellular energetics, the accumulation of reactive oxygen species (ROS) and the increased glucose excretion in the air–liquid surface." (PMID 35741067, 2022).
skeletal muscle disorder (1 paper, 2025). A disease involving the skeletal muscle tissue. "Importantly, the Adv‐CFTR treatment for 2 weeks increased the contractility, mass, fast/slow‐twitch muscle isoform ratio, and myofiber CSA of the treated gastrocnemii, compared to the Adv‐Ctrl treated ones, suggesting the potential of enhancing CFTR in rescuing skeletal muscle disorders." (PMID 39887939, 2025).
CFTR also shares sentences with these, for which no sentence is quoted: chronic sinusitis (14 papers); hearing loss (4); hemophilia A (4); Immunodeficiency (4); oligospermia (4); Osteopenia (4); portal hypertension (4); retinitis pigmentosa (4); sickle cell anemia (4); allergic dermatitis (3); Alzheimer disease (3); amyotrophic lateral sclerosis (3); Arrhythmia (3); developmental delay (3); Dubin-Johnson syndrome (3); endocrine disorder (3); gastrointestinal disease (3); gastrointestinal disorders (3); gastrointestinal tumors (3); gout (3); haemoglobinopathies (3); hemophilia (3); hepatopathy (3); hyperhomocysteinemia (3); ischemia (3); Lynch syndrome (3); lysosomal storage disease (3); neuroblastoma (3); osteoporosis (3); Parkinson disease (3).
A further 232 diseases each share a sentence with CFTR in 3 papers or fewer.